PTCH1 (patched 1)
Diseases named in the same sentence as PTCH1 in open-access papers (continued):
Sharing a sentence is not in itself a finding about the gene and the disease.
medulloblastoma (continued). "Ovarian fibromas, meningiomas and medulloblastomas appear to be more frequent in patients with constitutional pathogenic SUFU variants than PTCH1 variants." (PMID 33860896, 2021). "Among the SHH pathway genes, PTCH1 was mutated in 36% (12/33) of adult SHH medulloblastomas, and SMO was mutated in 27% (9/33)." (PMID 33172502, 2020). "Aberrations in SHH signaling, especially PTCH1 gene mutations leading to constitutively activated Smo, are found in ~25% of medulloblastoma." (PMID 33066274, 2020). "In particular, germline mutations in Patched1 have been found to be responsible for somatic mutations in medulloblastoma, and 50% of medulloblastomas present loss of PTCH1, loss of SUFU, or gain-of-function of SMO." (PMID 33050158, 2020). "Germline mutations in PTCH1 give rise to basal cell nevus (Gorlin) syndrome, which comes with an increased risk of different malignancies, including basal cell carcinoma and medulloblastoma." (PMID 32056145, 2020). "Somatic loss of the PTCH1 wild-type allele has been demonstrated in the sonic hedgehog subgroup of medulloblastomas (MBSHH) carrying germline PTCH1 mutations." (PMID 32436863, 2020). "One of the medulloblastomas showed a loss of heterozygosity in the PTCH1 gene, indicating a close clinical correlation with PTCH1 heterozygosity and medulloblastomas." (PMID 33066274, 2020). "The prevalence of medulloblastoma in GS is significantly higher in patients with the SUFU gene mutation (33%) than in patients with the patched 1 (PTCH1) gene mutation (<2%)." (PMID 33066274, 2020). "We then explored the opportunity for functional validation of candidate drivers of medulloblastoma that co-occur with PTCH1 mutations." (PMID 31204176, 2019). "Because PTCH1 and SMO work in primary cilia to generate GLI2‐A and GLI3‐A, primary cilia promote the progression of SHH medulloblastoma caused by mutations of PTCH1 and SMO." (PMID 30643718, 2019). "Human genetic studies have identified germline mutations in Ptch1 as the cause of Gorlin syndrome, which is characterized by basal cell carcinoma, medulloblastoma, cartilage tumors, and ectopic ossification during adolescence and early adulthood." (PMID 31482846, 2019). "Germline mutation in PTCH1 predisposes patients to medulloblastoma, with mutation in PTCH1 also occurring commonly in sporadic disease." (PMID 31204176, 2019). "One major developmental pathway associated with medulloblastoma formation is the Sonic hedgehog (Shh)/Patched 1 (Ptch1) pathway." (PMID 30657775, 2019). "To analyze a possible effect of 4SC‐202 treatment on GLI processing, we used Ptch1 deficient Med1 cells derived from a genetic mouse model of medulloblastoma." (PMID 29055107, 2018). "Loss‐of‐function mutations in PTCH1 elicit aberrant activation of the pathway and can lead to basal cell carcinoma and medulloblastoma." (PMID 30098229, 2018). "Radiation signature mutations in the form of interstitial deletions have been reported recently to account for loss of the Ptch1 locus on chromosome 13 in gamma ray-induced medulloblastomas in Ptch1 heterozygous mice." (PMID 28683078, 2017). "Later, PTCH1 mutations were associated with over-activation of the Hh pathway in basal cell carcinoma and medulloblastoma." (PMID 28948003, 2017). "Since there is a higher prevalence of PTCH1 andSMO mutations in adult SHH medulloblastomas, this predictsresponsiveness to inhibitors of the receptor SMO." (PMID 28713553, 2017). "Aberrant SHH signaling was first linked to medulloblastoma as Gorlin’s syndrome patients, harboring a mutated PTCH1 gene, exhibited an increased incidence of medulloblastoma." (PMID 29186899, 2017). "One of the hallmarks and critical events in the progression of medulloblastoma is the loss of Ptch1 expression, which deregulates Shh signaling." (PMID 29615598, 2016). "Taken together, these results suggest GADD34 heterozygous mutation results in the noticeable increase of medulloblastoma incidence in Ptch1+/− mice by moderately enhancing the ISR." (PMID 27802424, 2016).
medulloblastoma (continued). "Our previous study showed that PERK heterozygous deficiency reduces the incidence of medulloblastoma in Ptch1+/− mice." (PMID 27802424, 2016). "Moderate increase of the ISR via GADD34 heterozygous mutation increased the incidence of medulloblastoma in Ptch1+/− mice." (PMID 27802424, 2016). "We found that GADD34 heterozygous mutation noticeably increased the incidence of medulloblastoma in Ptch1+/− mice." (PMID 27802424, 2016). "Nevertheless, strong increase of the ISR via GADD34 homozygous mutation decreased the incidence of medulloblastoma in Ptch1+/− mice by enhancing pre-malignant GCPs apoptosis during the course of cell transformation." (PMID 27802424, 2016). "Surprisingly, GADD34 homozygous mutation significantly decreased the incidence of medulloblastoma in Ptch1+/− mice, which was associated with enhanced apoptosis of pre-malignant GCPs in young mice." (PMID 27802424, 2016). "Recent studies have highlighted that in 90% of BCCs and 30% of adult medulloblastomas, hyperactivation of HH pathway is associated to mutations in PTCH1." (PMID 27486983, 2016). "Loss of function mutations in PTCH1 are associated with development of various types of cancers, including medulloblastoma, pancreatic cancer and colorectal cancer." (PMID 26768750, 2016). "Sequencing of infant, children and adult medulloblastomas found PTCH1 mutations in approximately equal frequencies across all age groups." (PMID 26512695, 2015). "Mouse models with similar mutations in the PTCH1 gene also develop medulloblastomas histologically similar to human tumors." (PMID 26258793, 2015). "Then, we analyzed medulloblastomas for allelic imbalance at the Ptch1 locus, being the biallelic Ptch1 loss the major pathway to medulloblastoma development in this mouse model." (PMID 26452034, 2015). "Loss of one copy of Dicer induced SHH medulloblastoma with a similar time of onset and penetrance in Dicerfloxed/+; Nestin-Cre+; Ptch1+/-; Cdkn2c+/- compared to Dicer+/+; Ptch1+/-; Cdkn2c+/- mice, 76.5% (39/51) versus 62% (31/50), respectively." (PMID 26091048, 2015). "Shh medulloblastomas appear to be almost exclusively associated with deletions of chromosome 9q, which is also the location of the PTCH1 gene (9q22)." (PMID 25101241, 2014). "Molecular analysis of sporadic medulloblastomas commonly shows Patched-1 (PTCH1) mutations, although mutations in SMO and Suppressor of Fused (SUFU) have been described." (PMID 25101241, 2014). "Mutations in Ptch1 and Smo occur in patients with medulloblastoma (MB), an aggressive childhood cancer arising from cerebellar GNPs." (PMID 23671675, 2013). "The subtype of medulloblastoma with mutations in Shh pathway components, such as a negative regulator PTCH1, arises from cerebellar GNPs." (PMID 24143253, 2013). "The increased accumulation of proliferating GCPs in the EGL observed in the Ptch1+/− Nos2−/− genotype supposedly leads to a larger pool of cells susceptible to neoplastic transformation and is therefore likely to promote medulloblastoma development." (PMID 22438824, 2012). "Taken together, these results indicate that Nos2 deficiency promotes medulloblastoma development in Ptch1+/− mice through retention of proliferating GCPs in the external granular layer due to reduced Gap43 expression." (PMID 22438824, 2012). "Significantly, loss of MDM2 in Ptch1+/− mice, a model for Shh-mediated human medulloblastoma, impedes cerebellar tumorigenesis." (PMID 21437245, 2011). "P/LP variants in PTCH1 have been associated with infant medulloblastoma, and since our cohort has a limited number of infants this may be a factor." (PMID 39184053, 2024). "In addition, medulloblastoma in Ptch1+/–mice and renal cancer in Eker rats are caused by nonsense mutations associated with deletions spanning from several to hundreds of bases." (PMID 37824459, 2023).
medulloblastoma (continued). "For disease-specific iPSCs, it was reported that in teratomas with a homozygous PTCH1 mutation, medulloblastoma-like tissue was larger than in teratomas heterozygous for the PTCH1 mutation, which indicated the importance of PTCH1 in medulloblastoma formation and Hh-related tumors." (PMID 37460876, 2023). "The risk of medulloblastoma in PTCH1-related NBCCS was less than 2%." (PMID 35843976, 2022). "Likewise, the estimate for medulloblastoma associated with PTCH1 from gnomAD was 1 in 3356, giving an estimated penetrance of 0.37%." (PMID 33860896, 2021). "Interestingly, Gln-iPSCs with a heterozygous germline mutation of PTCH1 developed into medulloblastoma with a secondary somatic mutation, i.e. loss of heterozygosity (LOH), in PTCH1 in vivo." (PMID 32436863, 2020). "Loss of Ptch1 has been attributed with tumour formation in many organs, including the skin and liver, and in the brain, excessive Shh pathway activity has been well documented to be causative for medulloblastoma." (PMID 30657775, 2019). "SHH medulloblastomas show unregulated ligand-independent SHH pathway signaling due to mutations/alterations such as loss-of-function of PATCHED (PTCH1) or Suppressor of Fused (SUFU), gain-of-function of Smoothened (SMO), GLI1, GLI2, or MYCN, and/or other alterations." (PMID 31554835, 2019). "Indeed, patients with the autosomal dominant nevoid basal cell carcinoma syndrome are predisposed to BCC and medulloblastoma since they have inherited mutations in one allele of the PTCH1 gene, and BCCs from these patients lack the normal PTCH1 gene." (PMID 29987229, 2018). "Third, it was previously reported that the stimulatory G protein Gs acts as a tumour suppressor in basal cell carcinoma and medulloblastoma, which are caused by mutations in PTCH1 or SMO that results in constitutive SMO activation and high GLI transcriptional activity." (PMID 30148884, 2018). "Therefore, it is not surprising that we found the lack of effect of the GADD34 mutation on steady state levels of p-eIF2α in medulloblastoma in Ptch1+/− mice." (PMID 27802424, 2016). "The Shh binding protein Boc is upregulated in medulloblastomas and contributes to the cerebellar granule cell precursor expansion by facilitating aberrantly high Shh signaling, which leads to increased CyclinD1 activity and Ptch1 loss of heterozygosity." (PMID 29615598, 2016). "Thus, it is unlikely that GADD34 mutation influences medulloblastoma formation in Ptch1+/− mice through its effects on tumor cells." (PMID 27802424, 2016). "Our second patient with medulloblastoma showed the PTCH-1- N97fs*43 and K163fs*6 mutations." (PMID 25859559, 2015). "Loss of one copy of Dicer accelerated medulloblastoma formation in Ptch1+/-, Cdkn2c+/- animals." (PMID 26091048, 2015). "About one third of medulloblastomas show activated Hh signaling, and mutations influencing the signaling cascade could be commonly detected within the PTCH1 gene." (PMID 23303278, 2013). "Interestingly and perhaps not surprisingly, in the early clinical testing of vismodegib, a medulloblastoma patient who presented with widespread metastatic disease and had a PTCH1 mutation responded rapidly and achieved dramatic tumor regression." (PMID 23349881, 2013). "Distinct tumors, such as BCC and medulloblastoma, may harbor mutations in PTCH1 or SMO that leads to constitutive pathway activation in the absence of HH ligand." (PMID 21203400, 2010). "At least 25% of medulloblastoma sporadic tumors show PTCH1 mutations." (PMID 21059263, 2010).
medulloblastoma (continued). "The SHH pathway was first implicated in medulloblastoma when germline mutations in the PTCH1 gene were found to be the cause of Gorlin's syndrome, a congenital condition characterized by increased incidence of basal‐cell carcinoma, medulloblastoma and rhabdomyosarcoma." (PMID 19076778, 2009). "Activation of the SHH signaling pathway in medulloblastoma can occur by mutations in PTCH1." (PMID 18769486, 2008). "In addition, class I HDACs may also act at the level of GLI processing, as we found that 4SC‐202 treatment increased the level of Gli3R in Ptch1‐deficient mouse medulloblastoma cells." (PMID 29055107, 2018). "Finally, a SB medulloblastoma screen in Ptch1+/−mice identified candidate cancer genes and associated protein networks capable of distinguishing the molecular subgroups of human medulloblastoma, demonstrating the power of transposon screens to recapitulate the genetic changes in human cancer." (PMID 26481584, 2015). "A subset of medulloblastoma originates from granule cell precursors (GCPs) of the developing cerebellum and demonstrates aberrant hedgehog signaling, typically due to inactivating mutations in the receptor PTCH1, a pathomechanism recapitulated in Ptch1+/− mice." (PMID 22438824, 2012). "A recent investigation utilizing the CRISPR/Cas9 gene editing of Patched-1 (PTCH1) in hiPSCs led to the generation of a medulloblastoma-cerebellar organoid." (PMID 40498018, 2025). "Mutations in the PTCH1 gene (encoding Patched-1 receptor) and the SMO gene (encoding the Smoothened homolog) lead to abnormal pathway activation, resulting in medulloblastoma and basal cell carcinoma." (PMID 40115023, 2025). "In the setting of sporadic cancers, somatic deleterious mutations and deletions of PTCH1 and SUFU have been observed in a subset of BCCs and medulloblastomas." (PMID 37255594, 2023). "In another case, other researchers showed that PTCH1-null-induced pluripotent stem cells exclusively differentiate into immature ectodermal cells with large areas of medulloblastoma-like tissue." (PMID 37629084, 2023). "To date, only medulloblastoma in Ptch1+/− mice and renal tumors in Tsc2+/− Eker rats have been properly demonstrated (i.e. with evidence of copy number losses) to have an interstitial deletion as a radiation signature in solid tumors." (PMID 37117033, 2023). "The inhibition of the hedgehog pathway by smoothened homologue inhibitors such as cyclopamine and HhAntag results in the regression of medulloblastoma tumors in PTCH1 mutant mice." (PMID 38132264, 2023). "Interstitial deletion has been reported as a mutational signature of radiation exposure in multiple animal models including medulloblastoma of Ptch1 heterozygous mice and kidney tumors of Tsc2 heterozygous Eker rats." (PMID 36662808, 2023). "Taladegib is currently being investigated in a phase II clinical trial (NCT05199584) involving patients with solid tumors and PTCH1 loss of function mutations, which is a common mutation in SHH-activated medulloblastomas." (PMID 37568705, 2023). "This inhibitor has also been recently shown to inhibit the growth of allografts in nude immunodeficient mice of primary tumors derived from a high-frequency medulloblastoma murine model Ptch1+/−/Tis21KO medulloblastoma." (PMID 38033496, 2023). "In agreement with the demand for directed therapies, our animal facility is also producing the SHH MB mouse model with higher medulloblastoma by conditional deletion of PTCH1 in cerebellar granule cell precursors (Math1)." (PMID 36423085, 2022).
medulloblastoma (continued). "The percentages of the area occupied by medulloblastomas were significantly larger in PTCH1−/− teratomas than in PTCH1+/− teratomas." (PMID 35618979, 2022). "The PTCH1+/− mouse that developed medulloblastoma tumors exhibited dense cerebellar lesions that compress adjacent normal tissue." (PMID 36423085, 2022). "We previously reported that teratomas derived from NBCCS-iPSCs (PTCH1+/−) generated medulloblastoma-like tissues." (PMID 35618979, 2022). "The present results indicate the importance of PTCH1 in medulloblastoma formation and the suitability of these gene-edited iPSCs and PTCH1−/− teratomas as models for the formation of tumors, such as medulloblastomas and Hh-related tumors." (PMID 35618979, 2022). "The major difference between teratomas from NBCCS-iPSCs and gene-edited PTCH1−/− teratomas is that the latter mostly comprise ectodermal tissues and markedly larger areas were occupied by medulloblastoma-like tissues in the latter than in the former." (PMID 35618979, 2022). "Specifically, medulloblastoma was found in 3 out of 9 individuals (33.3%) with SUFU variants, but in only 2 out of 115 patients (1.7%) with PTCH1 variants." (PMID 33441926, 2021). "We have previously generated a mouse model (Ptch1+/−/Tis21KO), which displays high frequency spontaneous medulloblastoma, a pediatric tumor of the cerebellum." (PMID 34395258, 2021). "In a large series of medulloblastomas screened for germline mutations, all SUFU or PTCH1 PVs were observed exclusively in the SHH-medulloblastoma (SHH-MB) subgroup, with a frequency of 17/80 (21%) and 18/170 (11%) in infant and pediatric SHH MB, respectively." (PMID 33860896, 2021). "It is well known in literature the role of PTCH1 as a TSG in several tumors such as medulloblastoma and basal cell carcinoma." (PMID 34157951, 2021). "In these models, approximately 15% of mice with a heterozygous PTCH1 mutation develop tumors in their cerebella, resembling SHH group medulloblastoma in humans." (PMID 34436033, 2021). "Knockout of Trim32 resulted in a higher incidence of medulloblastoma formation in the Ptch1 ± mice and the upregulation of SHH target genes, suggesting a tumor suppressor effect from antagonizing SHH signaling." (PMID 33273457, 2020). "SHH is the predominant group in adult medulloblastomas, and adult SHH tumours are characterised by upstream pathway mutations in PTCH1 and SMO, whereas downstream pathway alterations such as SUFU mutations and MYCN amplifications are rare in this age group." (PMID 33172502, 2020). "In fact, nearly 90% of sporadic BCC and up to 33% of sporadic medulloblastomas show SHH pathway activation, caused most commonly by inactivating mutations in PTCH1 or more rarely by activating mutations in SMO." (PMID 32957513, 2020). "Sequence analysis of the microdissected cartilage and medulloblastoma derived from G11 iPSCs revealed heterozygous mutations of the PTCH1 gene and LOH of the PTCH1 gene, respectively." (PMID 32436863, 2020). "To determine if AHR has a direct role in SHH medulloblastoma in vivo, we conditionally deleted the Ahr gene in mouse cerebellar GCPs, either alone or in combination with medulloblastoma-initiating Ptch1 gene deletion." (PMID 31924815, 2020).